SDC1 (syndecan 1)
Diseases named in the same sentence as SDC1 in open-access papers (continued):
Sharing a sentence is not in itself a finding about the gene and the disease.
Sepsis (continued). "Serum syndecan-1 and sTM may be promising biomarkers for early diagnosis of sepsis, particularly for patients with septic shock." (PMID 36536028, 2022). "Furthermore, HA and syndecan-1 were elevated for at least the first 3 days in septic shock vs. severe sepsis patients." (PMID 35872762, 2022). "However, limited data exist regarding the relationship between syndecan-1, sTM, and organ dysfunction severity and their predictive value in sepsis." (PMID 36536028, 2022). "We hypothesized that HDIVC could reduce plasma cfDNA and syndecan-1 levels of subjects with sepsis-induced ARDS, compared to subjects receiving standard of care." (PMID 36297099, 2022). "A systematic review of 17 studies investigating the relationship between markers of glycocalyx degradation and outcomes in sepsis showed that concentrations of syndecan-1 and endocan were higher in patients who died, developed MODS or experienced renal failure." (PMID 36551905, 2022). "In this regard, it is noteworthy that elevation of circulating syndecan-1 was associated with inflammatory biomarkers of neutrophil activation, including MPO, and was predictive of adverse clinical outcomes in patients with sepsis due to pneumonia." (PMID 36119052, 2022). "Organ dysfunction (PELOD-2 ≥ 8) could bepredicted by the syndecan-1 level in the first 24 hours of sepsis,suggesting its significant pathophysiological involvement insepsis-associated organ dysfunction." (PMID 35081239, 2022). "Monitoring the progression of glycocalyx damage markers (e.g., HA or syndecan-1) may prove to be useful to assess the progression of sepsis and predict survival." (PMID 35872762, 2022). "While syndecan-1, HA and HS were significantly higher in septic shock patients compared to sepsis patients, and syndecan-1 was good at predicting progression to septic shock (81.8% sensitivity, 78.3% specificity), interestingly, it was not higher in non-survivors, vs. survivors." (PMID 35872762, 2022). "Whilst, after an acute injury, glycocalyx is degraded by HPA, and the level of glycocalyx components such as HS, SDC-1 and HA is elevated in the bloodstream, which could predict outcomes of patients with sepsis-induced organ dysfunction, including ARDS." (PMID 34217286, 2021). "SDC1 and MR‐proADM were the biomarkers showing the highest odds ratios for sepsis." (PMID 32073224, 2020). "In a pig model, the syndecan-1 level in plasma had tripled one hour after sepsis had been induced." (PMID 28830365, 2017). "Alternatively, plasma syndecan-1 levels might be used to identify subgroups of sepsis patients for therapy targeted at protection or restoration of the endothelial glycocalyx." (PMID 28986821, 2017). "Measurement of syndecan-1 levels in sepsis patients might be useful for identifying patients at high risk of organ dysfunction and mortality as well as those who could benefit from therapies targeted at protecting or restoring the glycocalyx." (PMID 28986821, 2017). "Regardless of etiology of sepsis, elevated syndecan-1 levels were associated with non-pulmonary organ dysfunction and in-hospital mortality." (PMID 28986821, 2017). "However, to our knowledge, this is the first large-scale study of syndecan-1 as a biomarker of risk of ARDS and other organ dysfunction in patients with sepsis." (PMID 28986821, 2017). "Finally, in a smaller cohort of 184 patients with severe sepsis or septic shock we found an independent association between high circulating syndecan-1 levels and coagulopathy evaluated by TEG, further linking endotheliopathy and coagulopathy also in sepsis." (PMID 28179016, 2017). "In addition, another study with 20 patients shows a significant increase in circulating syndecan-1 on sepsis onset." (PMID 27699168, 2016). "Moreover, there was a strong correlation between levels of IL-6 and syndecan-1 in both sepsis and surgery group." (PMID 27699168, 2016).
Sepsis (continued). "Previous studies investigating circulating syndecan-1 levels as a surrogate for endothelial glycocalyx damage have reported increased levels in trauma, sepsis, major vascular- and abdominal surgery, STEMI and OHCA patients, with the highest levels in non-survivors and/or the most sick patients." (PMID 25789868, 2015). "We have previously reported that experimental endotoxemia in healthy volunteers receiving a 4-h 0.5 ng/kg/h infusion of E. coli lipopolysaccharide did not result in significant changes of circulating levels of catecholamines, syndecan-1 or soluble thrombomodulin contrary to patients with sepsis." (PMID 25505423, 2014). "Previously, Murphy’s research showed that the extent of endothelial glycocalyx degradation (measured by a component named Syndecan 1) is associated with non-pulmonary organ dysfunction in subjects with sepsis and is associated with ARDS but only in the subgroup with non-pulmonary sepsis." (PMID 40404729, 2025). "In this study, patients with higher serum syndecan-1 levels after completion of sepsis-associated DIC treatment were found to have elevated DIC scores and death, suggesting that serum syndecan-1 level may be a predictive marker for sepsis-associated DIC treatment." (PMID 40740948, 2025). "However, since the HS content of SDC1 may vary depending on the stage of sepsis, we plan to analyze time-related fluctuations in serum sSDC1 patterns of various patients in a subsequent study." (PMID 41293540, 2025). "Understanding this dynamic process may provide a more integrated view of SDC1 biology in sepsis." (PMID 41293540, 2025). "Moreover, an essential role of the endothelium, particularly the endothelial glycocalyx, has emerged as having a central role in critical illness, and elevation of EG biomarkers such as Syndecan-1, heparan sulfate, hyaluronan can be related to EG-damage patient outcome, particularly with sepsis." (PMID 37842022, 2023). "Furthermore, weonly measured syndecan-1 on day 1 and day 5 after sepsis was diagnosed." (PMID 35081239, 2022). "As the syndecan-1 level has a good predictive valuefor significant organ dysfunction, clinically, the use of syndecan-1 in pediatricpatients may be useful to stratify pediatric sepsis patients based on severity andas a therapeutic guideline to avoid overtreatment." (PMID 35081239, 2022). "Syndecan-1 (SDC-1), the core protein in heparan sulfate proteoglycan, is found in the endothelial glycocalyx and shed into the blood in various systemic inflammatory conditions, including trauma, sepsis, acute respiratory distress syndrome, acute kidney injury and cardiovascular disease." (PMID 36237551, 2022). "Elevated serum syndecan-1 and sTM levels could be used to alert clinicians of endothelial injury, and in clinical treatment, clinicians should put more emphasis on endothelial function and protecting endothelial cells from injury during sepsis." (PMID 36536028, 2022). "Therefore, circulating syndecan-1 was measured in sepsis patients in our study." (PMID 34707618, 2021). "Therefore, syndecan-1 and ZO-1 were investigated in the current study in order to determine mechanism of glycocalyx shedding in the aortic endothelial cells following severe infection or sepsis." (PMID 26199464, 2015). "In addition, the administration of antithrombin preparations and rhTM for sepsis-associated DIC is known to have anticoagulant, anti-inflammatory, and vascular endothelial glycoprotective effects, which may have influenced the blood levels of syndecan-1." (PMID 40740948, 2025). "Another post hoc study of the RCT examined the effect of high-dose vitamin C in sepsis-induced acute respiratory distress syndrome (CITRIS-ALI), demonstrating attenuated syndecan-1 by the treatment with vitamin C." (PMID 38658435, 2024). "Thus, SDC1 may serve as a biomarker for the prognosis of children with sepsis." (PMID 37614234, 2023).
Sepsis (continued). "We measured day 1 and day 5 syndecan-1 levels as a marker for endothelial glycocalyxshedding and the PELOD-2 score as a tool to measure the severity of organdysfunction in pediatric sepsis and found that the two were correlated." (PMID 35081239, 2022). "The serum levels of HS, HA, and syndecan-1 are always used as the biomarker of EGL integrity and are detected in patients with sepsis, atherosclerosis, and diabetes." (PMID 35741101, 2022). "Circulating levels of soluble SDC1 and SDC3 have been reported to be increased during critical illnesses (including sepsis) compared with control patients." (PMID 34355516, 2022). "Prior studies have shown higher levels of cfDNA and syndecan-1 at the onset of sepsis and ARDS as predictors of increased level of sepsis, mortality rate, and likelihood of intubation." (PMID 36297099, 2022). "A rat model of sepsis found that AT-III reduced leucocyte adhesion and rolling and plasma syndecan-1 concentrations." (PMID 36551905, 2022). "In the present study, we explored the roles of vascular EGL and Sdc-1 protein in the pathophysiology of sepsis and tested the therapeutic effects of HMW-SH, using the setting of the double-hit injury murine model (Sdc-1 KO and WT mice) of sepsis." (PMID 33930030, 2021). "To study glycocalyx degradation in sepsis-induced ARDS, we measured plasma levels of syndecan-1, a marker for glycocalyx degradation." (PMID 28986821, 2017). "When assessing a 50% variation in serum syndecan-1 levels, five out of eight patients in the non-sepsis-associated DIC recovery group showed an increase, whereas none of the patients in the sepsis-associated DIC recovery group exhibited an increase." (PMID 40740948, 2025). "As HDIVC directly attenuates the rise of both syndecan-1 and cfDNA at 48-h, this may provide a partial pathway into the mechanism of mortality benefit with HDIVC in subjects with sepsis induced ARDS." (PMID 36297099, 2022). "Since SDC1 and SDC4 are known to influence the cargo of EVs, we cannot exclude the impact of SDC2 on the composition of MSC‐derived EVs and this influence on sepsis pathobiology." (PMID 34355516, 2022). "When compared with COVID-19 negative sepsis patients, COVID-19 positive patients had persistently higher soluble P-selectin, hyaluronic acid, and syndecan-1, particularly on ICU day 3 and thereafter." (PMID 35872762, 2022). "Plasma levels of angiopoietin-2, endocan, sVE-cadherin, and syndecan-1 were significantly higher in sepsis patients with severe AKI compared to those without severe AKI." (PMID 33541396, 2021). "In sepsis resuscitation, the limited rate of fluid resuscitation compared to the standard rate did not significantly reduce changes in syndecan-1 at 6 h." (PMID 33402229, 2021). "In the present study, we have shown that elevated circulating syndecan-1 on the first day of ICU admission may predict persistent thrombocytopenia and lethal outcome in patients with suspected sepsis." (PMID 34557532, 2021). "In this randomized controlled trial examining resuscitating patients with sepsis-induced hypoperfusion in the ED, the limited rate of fluid resuscitation compared to the standard rate did not significantly reduce changes in syndecan-1 at 6 h." (PMID 33402229, 2021). "Despite several publications described a degradation of glycocalyx during sepsis, we did not observe a difference for syndecan-1." (PMID 32546181, 2020). "In addition, the two patients who died did not recover from sepsis-associated DIC at the end of anticoagulant therapy and had serum syndecan-1 levels increased by > 30% after treatment." (PMID 40740948, 2025).
Sepsis (continued). "In an analysis of the correlation between Syndecan-1 levels and sepsis in 55 patients after major abdominal surgery, patients suffering from sepsis had higher levels of Syndecan-1 (90 ng/mL) than those without sepsis (17 ng/mL) on the first postoperative day." (PMID 40943808, 2025). "COVID + patients had higher levels of syndecan-1, a component of the endothelial glycocalyx, than either non-COVID sepsis patients (812 ± 65 ng/mL vs 283 ± 188 ng/mL, p = 0.0094) or healthy volunteers (812 ± 65 ng/mL vs 65 ± 10 ng/mL, p = 0.03 and 283 ± 188 vs 65 ± 10 ng/mL ng/mL, p = 0.02)." (PMID 37015925, 2023). "Indeed, administration of fresh frozen plasma to non-bleeding critically ill patients (45% sepsis patients) resulted in a significantly lower syndecan-1 plasma concentration when compared to plasma levels obtained before transfusion (565 vs. 675 pg/mL)." (PMID 35872762, 2022). "Furthermore, circulating levels of Syndecan-1, a core protein of the intact glycocalyx, increased tenfold in sepsis patients and correlated with PBR values, indicating that enzymatic shedding is a dominant mechanism of PBR increase in sepsis." (PMID 33741036, 2021). "Our data confirmed that disruption of the EGL makes pulmonary vasculature more prone to leak in sepsis, and the absence of Sdc-1 protein results in the early death of septic Sdc-1 KO mice, with significantly increased lung water content compared to septic WT mice." (PMID 33930030, 2021). "However, despite the known role of endothelial injury and activation in the pathogenesis of ARDS, the association between syndecan-1 and development of ARDS or other organ dysfunction in sepsis has not been well studied." (PMID 28986821, 2017). "Another post-hoc multicenter RCT analysis of albumin replacement in severe sepsis or septic shock (ALBIOS) reported a decrease of soluble VE-cadherin in the cohort receiving albumin but no significant changes in S1P and syndecan-1." (PMID 38658435, 2024). "In a prospective study of 21 sepsis patients PBR correlated positively with plasma concentrations of Ang-2 (R = 0.52, p = 0.03) but not with APACHE, SOFA, lactate or syndecan-1." (PMID 36551905, 2022).
COVID-19 (54 papers, 2020 to 2025). A disease caused by infection with severe acute respiratory syndrome coronavirus 2. "Applying meta-analyses to combine results allowed us to derive more evidence for syndecan-1 as a diagnostic and prognostic biomarker in COVID-19." (PMID 37542221, 2023). "In the current systematic review and meta-analysis, we aimed to assess the diagnostic and prognostic role of syndecan-1 in COVID-19." (PMID 37542221, 2023). "Plasma or serum levels of syndecan-1 on admission were found to be significantly elevated in patients with severe and critical COVID-19, which appears to be associated with mortality, intensive care unit (ICU) admission, and multiple organ damage." (PMID 36675479, 2023). "COVID-19 was associated with seemingly unperturbed barrier integrity (angiopoietin-2/1 ratio), enhanced glycocalyx degradation (syndecan-1) and elevated levels of angiogenic factors (PDGFs)." (PMID 35660785, 2022). "A high serum level of Syndecan-1 was associated with increased mortality in patients admitted to an ICU with COVID-19." (PMID 34861818, 2021). "This study aimed to determine the prognostic values of endothelial damage biomarkers (Syndecan-1 and thrombomodulin) in COVID-19 patients in China, as well as their associations with inflammation, coagulopathy, and mortality." (PMID 34861818, 2021). "Similarly, increased inflammatory mediators including IL-6, IL-8, and TNF-ɑ have been associated with elevated plasma concentrations of syndecan-1, hyaluronan, and HS in severe COVID-19." (PMID 38753622, 2024). "Endotheliopathy is marked by an increased level of plasma von Willebrand factor (VWF), E-selectin, plasminogen activator inhibitor-1 (PAI-1), soluble thrombomodulin (sTM), and syndecan-1, which is strongly associated with a poor outcome in patients with severe COVID-19." (PMID 36675479, 2023). "We found that plasma levels of syndecan-1 at T1 (>260 ng/mL) (p = 0.003), at T2 (>1018 ng/mL) (p = 0.03), and at T3 (>461 ng/mL) (p = 0.007) were associated with an increased 60-day mortality rate in patients with COVID-19." (PMID 36675479, 2023). "With the emergence of coronavirus disease of 2019 (COVID-19), several blood biomarkers have been identified, including the endothelial biomarker syndecan-1, a surface proteoglycan." (PMID 37542221, 2023). "SDC1 may contribute to early risk stratification of staged diseases such as COVID-19 and provide a pathobiological reference." (PMID 37007526, 2023). "COVID-19 was associated with higher plasma syndecan-1 levels as compared with other CAPs." (PMID 35660785, 2022). "Evidence points to COVID-19 patients having higher glycocalyx-degradation products such as SDC-1 and P-selectin, which may relate to thrombosis risk in severe COVID-19 patients." (PMID 36556051, 2022). "Therefore, its disruption and degradation, identified by high circulating levels of syndecan-1, hyaluronic acid and heparan sulfate in COVID-19 patients, contributes to an increased risk of thrombosis." (PMID 34682810, 2021). "However, severe COVID-19 was associated with marked increases in endocan and syndecan-1, which reflect pathological shedding of glycocalyx." (PMID 34214123, 2021). "Thus, we hypothesized that there may be association among Syndecan-1, proinflammatory cytokines, inflammation, endothelial damage and hypercoagulation in COVID-19 patients, which requires further investigation." (PMID 34861818, 2021). "Our finding is consistent with previous studies reporting early glycocalyx degradation and elevated circulating levels of syndecan-1 in patients with severe COVID-19." (PMID 40725559, 2025). "Activated leukocytes, such as neutrophils, release antimicrobial agents like myeloperoxidase (MPO), which has been shown to correlate with syndecan-1 shedding in COVID-19." (PMID 38753622, 2024).